PTPRT (protein tyrosine phosphatase receptor type T)
Diseases named in the same sentence as PTPRT in open-access papers (continued):
Sharing a sentence is not in itself a finding about the gene and the disease.
cancer (49 papers, 2014 to 2025). A tumor composed of atypical neoplastic, often pleomorphic cells that invade other tissues. "The discovery of PTPRT mutation as a favorable prognostic factor in BM expanded its known tumor-suppressive roles in primary cancers." (PMID 40808963, 2025). "We previously showed that the mutations in PTPRT were associated with the cancer metastasis of multiple cancer types." (PMID 38216925, 2024). "We previously found that PTPRT was downregulated in multiple cancer types and the mutation of PTPRT was associated with cancer early metastasis." (PMID 38216925, 2024). "Previous studies have demonstrated the association of certain cancer-related genes (e.g., PTPRT, MUC16, KMT2 family, FAT family genes etc.)with the response to ICI therapy." (PMID 37626083, 2023). "The discovery of other, less prevalent mutations, such as PTPRT, but potentially significant cancer‐causing mutations has substantial ramifications for understanding past and upcoming research employing these cell lines." (PMID 37525498, 2023). "In this study, we performed a comprehensive analysis to evaluate the association between PTPRD/PTPRT mutations and the efficacy of ICIs across multiple cancers." (PMID 36248841, 2022). "In this study, we systematically collected genetic and clinical data to analyze the association between PTPRD/PTPRT gene status and clinical response in pan-cancer patients treated with ICIs." (PMID 36248841, 2022). "We analyzed the association between PTPRD/PTPRT mutations and patient outcomes using clinical data and genomic mutations from TCGA pan-cancer cohort." (PMID 36248841, 2022). "Third, further analyses need to be conducted in the future due to the small sample sizes of PTPRD/PTPRT mutation patients of certain types of cancers, such as GBM, RCC, and HNSC, included in this study." (PMID 36248841, 2022). "The pan-cancer frequency of PTPRD or PTPRT (PTPRT/PTPRD) mutations was analyzed using data from TCGA." (PMID 36248841, 2022). "The lollipop plot depicted the pan-cancer distribution of different types of PTPRD/PTPRT mutations, with missense mutations being the most common subtype." (PMID 36248841, 2022). "In TCGA pan-cancer cohort (n = 10967), the PTPRT mutations were associated with poor prognosis of cancers (log-rank test, P = 0.016)." (PMID 35789644, 2022). "This study demonstrated that PTPRD/PTPRT mutations can be a good predictive biomarker for the efficacy of ICI treatment across multiple cancers." (PMID 36248841, 2022). "The TCGA pan-cancer dataset was analyzed to explore the correlation between PTPRD/PTPRT mutations and immune signatures." (PMID 36248841, 2022). "Fifth, the frequency of four DNA mismatch repair (MMR) gene mutations were higher in the PTPRD/PTPRT mutant cancer patients, compared with WT patients (all P < 0.001)." (PMID 36248841, 2022). "This demonstrated the specificity of PTPRT mutation as a candidate biomarker for cancer metastasis across multiple cancer types." (PMID 35789644, 2022). "PTPRT functions as a tumor suppressor gene, and is mutated in colon, lung, stomach, and skin (melanoma) cancers." (PMID 34440220, 2021). "PTPRD or PTPRT are identified as tumor suppressor, which is frequently inactivated and mutated in various human cancers." (PMID 34123798, 2021). "Through integrative analysis of cancer genetic and clinicopathological data, deleterious alterations in PTPRT/PTPRD were associated with bevacizumab resistance, as indicated by a poor response rate and shorter survival." (PMID 30200630, 2018). "We postulate five of eight PTPRT mutations detected in our cohort to be deleterious, one variant being a truncating variant and the other four being cancer-recurrent missense mutations." (PMID 30200630, 2018). "Like PTPRD, PTPRT is inactivated by mutation in many cancers, including lung cancer, gastric cancer, and head and neck SCC, and it is most frequently mutated in colorectal cancer (CRC)." (PMID 30208623, 2018).
cancer (continued). "Given that PTPRT is a tumor suppressor, it would be challenging to target PTPRT mutations in cancers." (PMID 27447856, 2017). "Of the genes commonly found in both the samples, PTPRT has been previously reported to be frequently mutated in cancer patients." (PMID 28324520, 2015). "Furthermore, as a well-known tumour suppressor gene, mutations in PTPRT were associated with the occurrence of cancer." (PMID 38216925, 2024). "Furthermore, PTPRT mutation is associated with poor progression-free survival in pan-cancer and NSCLC." (PMID 35789644, 2022). "We found that PTPRD/PTPRT mutations were a favorable biomarker of pan-cancer ICI treatment." (PMID 36248841, 2022). "PTPRD/PTPRT mutations are common mutations in multiple cancer types, but there have only been a few studies that have been conducted on the role of this type of mutations in pan-cancer patients treated with ICIs." (PMID 36248841, 2022). "PTPRD/PTPRT mutations may be a potential biomarker for predicting ICI treatment responsiveness in multiple cancer types." (PMID 36248841, 2022). "Notably, fourteen DDR gene mutations were significantly more prevalent in PTPRD/PTPRT mutant cancer patients than in WT patients (all P < 0.001)." (PMID 36248841, 2022). "PTPRT mutations were identified in various cancer types and are particularly common in CRC." (PMID 30200630, 2018). "Furthermore, it has been shown that post-translational modification of PTPRT by glycosylation reduces its activity by causing it to dimerize, which has been shown to result in enhanced cancer cell migration via the activation of STAT3-mediated signaling." (PMID 30208623, 2018). "Moreover, PTPRT is frequently mutated in human cancers such as colon, lung, skin and gastric cancer." (PMID 29558404, 2018). "However, the corresponding kinases of PTPRT substrates are potential therapeutic targets for patients whose cancers harbor PTPRT mutations." (PMID 27447856, 2017). "Moreover, recent whole-exome sequencing of various human cancers revealed that PTPRT is frequently mutated in a variety of human cancer types." (PMID 27447856, 2017). "However, the clinical pan-cancer significance of PTPRD/PTPRT mutations in treated with ICIs remains unknown." (PMID 36248841, 2022). "However, the pan-cancer association between PTPRD/PTPRT mutation and the efficacy of ICIs remains unclear across pan-cancer patients." (PMID 36248841, 2022). "However, PTPRT showed higher mutation frequency in cancer, which accorded with several studies." (PMID 36341348, 2022). "PTPRT was also found to be the most epimutated PTP in 4 of the 5 cancer tissues analysed (CRC = 78%, Stomach = 55%, Oesophagus = 42% and Pancreas = 19%) and second most epimutated in Lung (21%)." (PMID 38475971, 2024). "As CCK-8 assays showed, PTPRT-knocked-down A549 cells displayed enhanced cell proliferation, while PTPRT-overexpressing H1975 cells had decreased cell proliferation, suggesting an inhibitory role of PTPRT in cancer cell proliferating." (PMID 38216925, 2024). "Mutations in TET2, PTPRT, and LRP1B are associated with favorable responses to ICIs in other cancer types." (PMID 37654198, 2023). "Another report, however, tones down the frequency and importance of PTPRT alterations in sporadic human cancers." (PMID 36755664, 2022). "In the Samstein cohort, prolonged overall survival (OS) was observed in PTPRD/PTPRT mutant cancers, compared with wild-type cancers (mOS: 40.00 vs 16.00 months, HR = 0.570, 95%CI: 0.479-0.679, P < 0.0001)." (PMID 36248841, 2022). "Second, most immuno-stimulators, such as MICB, MICA, CD80, ICOS, CD27, and various TNFSFs (all P < 0.05), were expressed at higher levels in PTPRD/PTPRT mutant cancers, compared with the WT." (PMID 36248841, 2022). "First, the enrichment levels of 29 immune signatures were evaluated between PTPRD/PTPRT mutant and WT cancers." (PMID 36248841, 2022). "In contrast, CXCR3, an anti-tumor receptor of ICIs, was shown to be upregulated in PTPRD/PTPRT mutant cancers (P <0.001)." (PMID 36248841, 2022).
cancer (continued). "To validate the immunotherapy implications of PTPRT mutations, we employed 1661 ICI‐treated pan‐cancer patients with targeted‐NGS." (PMID 34862763, 2022). "Most immune cells, including memory B cells, CD8+ T cells, Tfh, and macrophage M1 cells, were more abundant in PTPRD/PTPRT mutant cancer patients (all P < 0.05)." (PMID 36248841, 2022). "DDR and MMR gene mutations, which can increase tumor immunogenicity and promote anti-tumor immunity, were more frequent in the PTPRD/PTPRT mutant cancer patients than in the WT patients." (PMID 36248841, 2022). "In line with the results of MSI sensor score, a higher MSI MANTIS score was found in PTPRD/PTPRT single-mutant or double-mutant cancers, compared with WT patients (P < 0.0001)." (PMID 36248841, 2022). "Four of the five NF2 mutations present were approximately clonal (cancer cell fraction >0.75), while two out of three FAT1, PTPRT, and EP300 mutations each were approximately clonal." (PMID 35288096, 2022). "In TCGA pan-cancer cohort, survival analysis showed that the OS was worse in patients with PTPRD/PTPRT mutations than in the WT (mOS, 65.52 vs 81.11 months, HR = 1.119, 95%CI: 1.018-1.228; P = 0.014)." (PMID 36248841, 2022). "The PTPRD/PTPRT mutant cancer patients had a significantly higher MSI sensor score, compared with WT patients (P < 0.0001)." (PMID 36248841, 2022). "In the Samstein cohort, the univariate analysis showed that cancer type, TMB, treatment type, and PTPRD/PTPRT mutations were statistically significant in predicting OS in patients receiving ICIs." (PMID 36248841, 2022). "The first PTP superfamily-focused screen for mutations in cancer specimens highlighted frequent alterations in six classical PTP genes, with PTPRT being the number one hit putting a tumor suppressor function for the encoded RPTPρ in the limelight." (PMID 36755664, 2022). "Recent two studies provided in vivo and in vitro evidence and demonstrated that PTPRT normally acts as a cancer suppressive mediator in colon tumor." (PMID 34862763, 2022). "Since PTPRT is a tumor suppressor in cancer, we elucidated the expression landscape of PTPRT in tumorigenesis." (PMID 35789644, 2022). "Other potential immune checkpoints, such as LAG3, CD96, PDCD1, BTLA, IDO1, and TIGIT, were also enriched in PTPRD/PTPRT mutant cancers." (PMID 36248841, 2022). "Another subgroup analysis conducted based on cancer types showed that PTPRD/PTPRT mutant patients treated with ICIs had significantly longer OS than WT patients in NSCLC and SKCM, which is consistent with the results of previous studies." (PMID 36248841, 2022). "The epigenetic suppression (promoter hypermethylation) of PTPRT occurs in several human cancers, but most notably in CRC (78.7%, 289/367 tumors analyzed)." (PMID 34440220, 2021). "Many human cancers show aberrant hypermethylation of the PTPRT promoter, which results in the decreased expression of PTPRT mRNA." (PMID 30208623, 2018). "PTPRT mutations improved survival and enhanced immunotherapy response in NSCLC and SKCM patients, which suggests that PTPRT may serve as a pan-cancer biomarker for immune checkpoint inhibitor efficacy." (PMID 40808963, 2025). "Similarly, a higher TCR Shannon Score was observed in the PTPRD/PTPRT single-mutant or double-mutant cancers, compared with WT patients (P < 0.01)." (PMID 36248841, 2022). "In addition, CXCR2 and CXCR4, which are associated with pro-tumor in ICIs, were shown to be lower in PTPRD/PTPRT mutant cancers compared with WT (both P < 0.01)." (PMID 36248841, 2022). "Overall, the results of this study demonstrated that PTPRD/PTPRT mutations are correlated with a poor prognosis and that PTPRD/PTPRT mutations might act as a pan-cancer biomarker for the prediction of ICI treatment efficacy." (PMID 36248841, 2022).
cancer (continued). "Notably, the significant upregulation of MHC I molecules was observed in PTPRD/PTPRT mutant cancers." (PMID 36248841, 2022). "In addition, the MSI sensor score was significantly higher in the PTPRD and PTPRT double-mutant cancers than in the single-mutant cancers (P < 0.0001)." (PMID 36248841, 2022). "In addition, elevated M1 infiltration and decreased M2 infiltration levels were observed in PTPRD/PTPRT mutant cancer patients, which can enhance anti-tumor immunity." (PMID 36248841, 2022). "In this study, the further enrichment of immune signatures, including CD8+ T cells, Tfh, B cells, DCs, cytotoxic activity, and pro-inflammation, were observed in PTPRD/PTPRT mutant cancers, indicated of the formation of an enhanced anti-tumor immune microenvironment." (PMID 36248841, 2022). "We calculated the mutation rate of the ROS1 and PTPRT genes for each cancer type and found them not to be high." (PMID 35197093, 2022). "Furthermore, the expression levels of CXCL9, CXCL10, CXCL11, and their receptor CXCR3, which perform anti-tumor roles in ICI treatment, were found to have increased in PTPRD/PTPRT mutant cancer patients." (PMID 36248841, 2022). "In this study, prolonged mOS was observed in PTPRD/PTPRT mutant patients who received ICI treatment, compared with the WT, across multiple cancers in two independent ICI-treated cohorts, confirming the prediction ability of PTPRD/PTPRT mutations for the efficiency of ICI treatment." (PMID 36248841, 2022). "Several studies showed overexpressed PTPRT might inhibit tumor cell growth acting as a putative tumor suppressor in cancer cell culture." (PMID 34414233, 2021). "However, given that PTPRT normally functions as a tumor suppressor and that its function is lost in cancer, it would be extremely difficult to reactivate PTPRT function in tumors." (PMID 27447856, 2017). "Given that there are more DEGs associated with PTPRT in LUAD than in LUSC, and these DEGs are enriched in cell cycle-related pathways, we hypothesized that the downregulation of PTPRT in LUAD may have an impact on the cell proliferation of cancer cells." (PMID 38216925, 2024). "However, to the best of our knowledge, the association between PTPRT and cancer metastasis has not been investigated through a comprehensive analysis of large clinical datasets." (PMID 35789644, 2022). "However, all five non-responders who harbored mutations of the TSG PTPRT had previously observed cancer variants or truncating variants, whereas this was not the case for any of the three responders with PTPRT variants." (PMID 30200630, 2018). "Further analysis into the role of PTPs and DUSP revealed PTPRT is the most ubiquitously epimutated PTP, 43% of all cancer individuals showed hypermethylated PTPRT promoters." (PMID 38475971, 2024). "Mechanistically, PTPRD/PTPRT mutations are strongly associated with high TMB, high MSI score, and an enhanced anti-tumor microenvironment, thus PTPRD/PTPRT mutations may be a promising biomarker for the prediction of the ICI treatment response in several cancers." (PMID 36248841, 2022). "Additionally, PTPRD/PTPRT mutations were strongly associated with a higher TMB, MSI score, TCR score, higher levels of immune cell infiltration, and enriched immune-related signatures, indicating an enhanced level of anti-tumor immunity in PTPRD/PTPRT mutant cancer patients." (PMID 36248841, 2022).
cancer (continued). "On the other hand, inhibition of negative regulators such as PIAS3, SOCS1 and 3 and several cellular phosphatases (SHP1 and 2, PTPRD, PTPRT, PTPN1 and 2, DUSP22) can also lead to STAT3 activation in cancer." (PMID 35145111, 2022). "PTPRD and PTPRT (PTPRD/PTPRT) are the phosphatases of JAK-STAT signaling, a critical pathway in anti-cancer immunity regulation." (PMID 36248841, 2022). "There was only one tumor suppressor (CSF2) and one cancer census gene in Cluster 3 (USP6); there are four tumor suppressors (GALR1, IRF4, PTPRT and SOX11) and one more cancer census gene in Cluster 4 (NRG1)." (PMID 28198667, 2017). "Moreover, by using the same evaluation criteria, we identify new biomarkers whose impact on drug response spans multiple cancers, including SALL4, B2M, BAP1, CCDC6, ERBB4, FOXA1, GRIN2A, and PTPRT." (PMID 39083502, 2024). "The expression of wild-type PTPRT, but not mutant forms, inhibited cell growth in human cancer cells." (PMID 38920970, 2024). "Importantly, higher PD-L1 and CTLA4 expression levels were observed in the PTPRD/PTPRT mutant cancer patients, compared with WT patients, suggesting that ICI treatment is more applicable for PTPRD/PTPRT mutant cancer patients." (PMID 36248841, 2022). "In total, recurrent (>3) MEI were observed in 329 protein-coding genes of which 28 genes are annotated in the Cancer Gene Consensus with either oncogenic (ALK1, ERBB4, TSHR, PREX2, CTNNA2, CTNND2) or tumour suppression roles (EBF1, LRP1B, PTPRD, GPC5, ROBO2, PTPRT)." (PMID 35301290, 2022). "Finally, the nomogram model based on the four factors, cancer type, TMB, treatment type, and PTPRD/PTPRT gene status, indicated a good accuracy in predicting the 1-, 3-, and 5-year survival of pan-cancer patients treated with ICIs." (PMID 36248841, 2022). "Five missense mutations in the most commonly altered PTPRT were found to reduce phosphatase activity, and expression of wild-type but not a mutant PTPRT in human cancer cells inhibited cell growth." (PMID 34414233, 2021). "Based on the mutation profiles in three genes (ROS1, SPEN, and PTPRT), we defined the TMB prognostic score that could predict cancer survival prognosis in the immunotherapy setting but not in the non-immunotherapy setting." (PMID 36911742, 2023). "The results demonstrated that the TCR Richness Score was notably higher in both the PTPRD/PTPRT single-mutant and double-mutant cancers, than in WT patients (P < 0.001), while there was no statistical difference between PTPRD/PTPRT single-mutant and double-mutant patients (P > 0.05)." (PMID 36248841, 2022).